ENSG00000212618
Synonyms: LOC124904114
Gene: Small nucleolar RNA gene on chromosome 17 (18,943,999 to 18,944,073, forward strand). Ensembl gene ENSG00000212618.
Gene Ontology:
Biological process: RNA processing
Cellular component: nucleolus
Homologues: Paralogues in human: SNORD68 (67% identical).